EPO (erythropoietin)
Diseases named in the same sentence as EPO in open-access papers (continued):
Sharing a sentence is not in itself a finding about the gene and the disease.
anemia (continued). "Blood transfusion therapy or treatments with erythropoiesis-stimulating agents such as recombinant erythropoietin are the present front-line therapies for anemia associated with ineffective erythropoiesis." (PMID 32759740, 2020). "Gastrointestinal bleeding can also cause an uncorrectable anemia despite proper supplementation of erythropoietin and iron." (PMID 33167896, 2020). "Treatment of anemia with erythropoietin (EPO) was associated with great benefits for some patients but not all." (PMID 31979104, 2020). "Almost all patients undergoing maintenance HD have anemia, mainly due to decreased erythropoietin production or a functional or absolute iron deficiency." (PMID 33167896, 2020). "This review underlies the physiopathology of anemia in CKD focusing on a potential mechanism of EPO on iron regulation in uremic condition." (PMID 32899941, 2020). "In end-stage renal disease population, anemia is a well-recognized risk factor for all-cause mortality, occurring mainly due to erythropoietin deficiency." (PMID 32695504, 2020). "Recombinant human EPO (rhEPO) was shown to be comparable to natural EPO in 1986 and, in 1987, synthetic EPO was first used to treat anemia associated with end-stage renal disease." (PMID 31650290, 2020). "Erythropoietin (EPO) analogs are a major therapeutic approach to treating anemia from EPO deficiency in CKD." (PMID 33013483, 2020). "In conclusion, anemia associated with CKD is a multifactorial condition that can be induced by EPO and/or iron deficiency." (PMID 32899941, 2020). "Previous studies have reported a significant correlation between carnitine deficiency and the erythropoietin resistance index, and improvement of erythropoiesis-resistant anemia by carnitine supplementation in patients undergoing hemodialysis." (PMID 32003308, 2020). "Carnitine deficiency is associated with EPO-resistant anemia, intradialytic hypotension, cardiomyopathy, and skeletal muscle dysfunction." (PMID 33013483, 2020). "The administration of vitamin D analogs has been linked with the amelioration of anemia and/or the reduction in EPO needs." (PMID 31979104, 2020). "A prominent example of the use of this concept is hyperglycosylated erythropoietin (EPO), marketed as Aranesp® (darbepoetin-α) and used for the treatment of anaemia associated with myelosuppressive chemotherapy and chronic renal insufficiency." (PMID 33096803, 2020). "In kidney transplant patients, the improved outcomes associated with the correction of anemia with EPO is erythropoiesis-independent and caused by inhibition of T-cell immunity via the EPO-receptor on T cells." (PMID 32635646, 2020). "This resulted in progressive mesangioproliferative glomerulonephritis, mesangial sclerosis, and interstitial fibrosis with progressive anemia due to loss of erythropoietin production by fibroblasts." (PMID 31943786, 2020). "EPO-induced bone loss is therefore dose-dependent and mostly irreversible at doses that offer only a minor advantage in the treatment of anemia." (PMID 32471308, 2020). "ACE inhibitor-associated anemia is due to the suppression of erythropoietin production, in response to A-acetyl-seryl-aspartyl-lysyl-proline accumulation in plasma." (PMID 31655853, 2020). "The causes of anaemia in patients with end-stage renal disease include a relative deficiency in erythropoietin production and complex clinical conditions." (PMID 32993543, 2020). "The relationship between the stage of cancer and the concentration of endogenous erythropoietin and the degree of anemia associated with it is currently being intensively studied." (PMID 32560029, 2020). "An impaired EPO production that causes anemia, can be found in patients with chronic kidney disease (CKD)." (PMID 33330669, 2020). "Erythropoietin (EPO) is a hormone made in the kidney that induces new red blood cell production in the bone marrow in response to anemia or blood loss." (PMID 32982979, 2020).
anemia (continued). "Anemia associated with impaired kidney function is defined as renal anemia, and its main cause has been established to be impaired erythropoietin (EPO) production in the kidney." (PMID 32998272, 2020). "In recent years, EPO has captured the attention of surgeons for its excellent efficacy in improving perioperative anemia caused by massive blood loss." (PMID 33213494, 2020). "The main causes of anemia in maintenance hemodialysis (MHD) patients are erythropoietin and iron deficiency." (PMID 33293895, 2020). "The same group has shown in the murine 5/6 nephrectomy model that FGF23 contributes to anemia in CKD by suppressing EPO, inducing iron deficiency, and increasing apoptosis." (PMID 32823844, 2020). "Disorders of kidney function can lead to inadequate EPO production, and compromised release of EPO from the defective kidney with subsequent impairment of erythropoiesis is the primary cause of anemia in chronic kidney disease." (PMID 32512916, 2020). "Human recombinant erythropoietin (rEPO) has been widely used to treat CKD-associated anemia and is known to possess organ-protective properties that are independent from its well-established hematopoietic effects." (PMID 32184703, 2020). "Since obtained Food and Drug Administration (FDA) license for clinical use, EPO and its analogs rHu-EPO have been used for treatment of the anemias caused by chronic renal failure, malignancies and proved to be effective." (PMID 33213494, 2020). "Although anemia can be caused by a large variety of reasons, anemia due to kidney damage is attributed to decreased production of EPO by the kidneys, leading to suppression of erythropoiesis." (PMID 33143240, 2020). "The best treatment options for anemia and iron deficiency are EPO-stimulating and iron supplementation agents; nonetheless, their use in hemodialysis or peritoneal dialysis patients is known to be less effective than that in adults." (PMID 30700016, 2019). "EPO treatment in extremely low birth weight infants appears to be well tolerated with no excess morbidity or mortality, and, in addition to improving anemia, is associated with overall benefit in developmental assessment and cognitive development." (PMID 32038269, 2019). "In the whole cohort, an unadjusted logistic regression model showed that high EPO levels were associated with the presence of anemia (Odds ratio 1.32 per 1 SD increase in log-transformed EPO, 95% CI: 1.02–1.71)." (PMID 31619722, 2019). "The erythropoietin dysregulation, caused by early damage to renal tubules, has been suggested as one of the contributors to anemia in patients with diabetes." (PMID 31496893, 2019). "Evaluating the iron availability for erythropoeisis is crucial in treating anaemia patients with CKD.Iron deficiency can interfere with the response to EPO and DA-α and affecting the efficacy." (PMID 30866856, 2019). "Erythropoiesis is impaired by iron restriction, suppression of EPO production and shortened life-span of erythroid progenitors, all culminating in iron-deficiency anemia." (PMID 31614529, 2019). "There are conflicting reports on the adverse effects of erythropoietin (EPO) for the management of cancer-associated anemia." (PMID 30622244, 2019). "Anemia of CKD is a multifactorial process due to relative EPO deficiency, uremic-induced inhibitors of erythropoiesis, shortened erythrocyte survival, and disordered iron homeostasis." (PMID 31915448, 2019). "The work performed by Rivkin and his colleagues has uncovered the mechanism that inflammation increases blood levels of MIR122, by which the expression of EPO in the kidneys is reduced and anemia is caused." (PMID 31915448, 2019). "Anemia associated with kidney injury, inflammation, and failure is attributed to inadequate EPO production and the shortened erythrocyte life span due to uremic toxins that are accumulated in the blood because of renal dysfunction." (PMID 30936264, 2019).
anemia (continued). "Although the pathogenic mechanisms of anemia are multiple, erythropoietin deficiency appears as the dominant factor." (PMID 31412807, 2019). "This study therefore determined the prevalence of anti-EPO antibody production and assessed its association with malaria and malaria-related anaemia in humans." (PMID 30894794, 2019). "Cytokines like TNF-α blunts erythropoietin effect and IL-1, IL-6 and interferon-γ interfere with iron metabolism causing anemia." (PMID 31387568, 2019). "Anti-EPO antibodies have been implicated in the anaemia associated with many diseases including HIV-1/AIDS, systemic lupus erythematosus, and pure Red Cell Aplasia among others." (PMID 30894794, 2019). "A novel therapeutic approach to correct CKD-associated anemia is the induction of EPO synthesis by stabilizing hypoxia-inducible factors (HIFs) with prolyl hydroxylase inhibitors (PHIs)." (PMID 32009983, 2019). "Studies have suggested that sepsis-related anemia can be caused by fluid loading-related hemodilution, iatrogenic blood loss, and decreases in iron supply, erythropoietin (EPO) production and erythrocyte lifespan." (PMID 31183575, 2019). "Anemia is generally caused by the dysfunction of erythropoietin (EPO) production, stimulating the proliferation and differentiation of erythroid precursor cells." (PMID 30621672, 2019). "EPO received approval in 1989 from the U.S. Food and Drug Administration for clinical treatment of anemia associated with chronic renal failure due to insufficient EPO production, which has markedly improved treatment of this disease." (PMID 32038269, 2019). "Hypoxia-inducible factor (HIF) stabilizers, also known as HIF prolyl hydroxylase inhibitors (PHI), are promising candidates to treat CKD-associated anemia by increasing erythropoietin synthesis." (PMID 32009983, 2019). "Treatment of anemia with EPO was associated with improved neuropsychological test performance and electroencephalography measurements in uncontrolled studies of patients with ESRD conducted in the early 1990s." (PMID 31484803, 2019). "EPO has also been demonstrated to exert protective effects in the kidneys and lungs of mice with sepsis, but EPO deficiency contributes to anemia development in patients with sepsis." (PMID 31183575, 2019). "Patients who present with low sEPO levels associated with anaemia before treatment appear to respond more readily to EPO." (PMID 31508719, 2019). "Anemia in CKD patients is a multifactorial process associated with a relative erythropoietin (EPO) deficiency, uremic-induced inhibition of erythropoiesis, shortened erythrocyte survival, and disordered iron homeostasis." (PMID 31375077, 2019). "In the case of chronic kidney disease (CKD)-associated anemia, EPO analogues or erythropoiesis-stimulating agents (ESA) have been used to increase RBC production from the bone marrow." (PMID 31332228, 2019). "Iron deficiency, together with other factors such as insufficient erythropoietin production by the kidneys and hyporesponsiveness to erythropoietin, cause anaemia in these patients." (PMID 30630452, 2019). "In the EPOANE trial, which led to licensing of EPO alfa in the indication of low-risk MDS with anemia, erythroid hematological improvement (HI-E, IWG 2006) was achieved in 32% of EPO treated patients compared to 4% of patients receiving placebo." (PMID 31394818, 2019). "Iron deficiency, inflammation, and decreased EPO production cause anemia in ESRD, and EPO therapy leads to the alleviation of the adverse effects of anemia." (PMID 31217925, 2019). "This study therefore established the prevalence of anti-EPO antibodies and assessed its association with malaria and malaria-related anaemia among Ghanaian children." (PMID 30894794, 2019). "After excluding patients with anemia of known etiologies (i.e., ID and inflammation), low EPO levels were associated with the presence of anemia." (PMID 31619722, 2019).
anemia (continued). "The main causes for anemia are iron deficiency and deficient erythropoietin (EPO) production in the renal tubular cells." (PMID 31551803, 2019). "Patients with diabetes and renal insufficiency have a higher risk of developing anemia associated with decreased production of erythropoietin by the failing kidneys." (PMID 31498832, 2019). "Circulating antierythropoietin (anti-EPO) antibodies have also been implicated in malaria and malaria-related anaemia in mice." (PMID 30894794, 2019). "In generally, ESAs like recombinant erythropoietin (EPO) and glycosylated forms (darbepoetin) are currently the first-line treatment of anemia in lower-risk MDS." (PMID 31394818, 2019). "Anemia prevalence in CKD patients increases from 26% to 75% when the renal function decreases from > 60 ml/min to < 15 ml/min most probably because of EPO deficiency." (PMID 29357391, 2018). "The effects of EPO treatment on critical illness-associated anemia and especially sepsis-associated anemia are debated." (PMID 29977234, 2018). "In CKD, the main causes of anemia are deficiency of erythropoietin, iron-restricted erythropoiesis and anemia of the chronic disease (ACD)." (PMID 30236065, 2018). "This has been impressively demonstrated for a hyperglycosylated EPO variant (darbepoetin alfa) that is glycosylated at two additionally introduced N‐glycosylation sites and has been approved for treatment of anaemia." (PMID 29479800, 2018). "CKD‐related anaemia is usually considered the result of the progressive loss of EPO‐producing interstitial cells." (PMID 28857467, 2018). "Recombinant human erythropoietin (rHuEPO) treatment has been employed to correct CKD associated-anemia as to improve the quality of patients’ life." (PMID 29615029, 2018). "Anemia resulting from reduced erythropoietin production has been cited as an important cause of fatigue in this population." (PMID 30197740, 2018). "Erythropoietin (EPO) deficiency remains the major cause of anemia in CKD patients due to the decrease in renal EPO production." (PMID 29357391, 2018). "The elevation of EPO seen in carriers of p.Gln82Ter in Iceland is likely a compensation for this hypo-responsiveness which would cause anaemia given normal EPO levels." (PMID 30271932, 2018). "For example, characterization of a cytokine erythropoietin (EPO) mutation known to cause severe anemia in humans showed that this mutation causes a selective impairment of downstream signal transduction in erythroid cells." (PMID 29983915, 2018). "Others suggested that CAN is a strong predictor of nephropathy and participates in the progression of chronic kidney disease through deficient erythropoietin production and anemia." (PMID 29693021, 2018). "Allograft dysfunction with subsequent reduced erythropoietin production is one of the major causes of post-transplant anemia." (PMID 30155279, 2018). "Key processes in CKD underlying the development of anemia are erythropoietin (EPO) deficiency and functional iron deficiency (FID), typically managed with use of iron, blood transfusion, or administration of an exogenous ESA." (PMID 29382128, 2018). "Treating patients with ESA while they suffer from other causes of anemia will lead to EPO resistance." (PMID 29357391, 2018). "As carnitine is eliminated by hemodialysis (HD), dialysis patients are particularly susceptible to carnitine deficiency and, consequently, to hypotension and erythropoietin low-responsiveness anemia." (PMID 29616582, 2018). "Such an inflammatory state is associated with adverse outcomes, including anemia and erythropoietin hyporesponsiveness, malnutrition, impaired quality of life and, above all, exceedingly high cardiovascular disease with increased mortality and hospitalization." (PMID 30181461, 2018). "Dialysis patients easily suffered from anemia due to endogenous erythropoietin deficiency, shortened RBC survival, and uremic inhibitors." (PMID 30741617, 2018).
anemia (continued). "As summarized by Greenbaum, there are many causes of anemia, including a reduction in erythropoietin production and iron deficiency." (PMID 30155452, 2018). "Acute rejection can cause post-transplant anemia due to decreased erythropoietin production and disturb the binding and transport of iron and folate through systemic inflammatory response." (PMID 30155279, 2018). "Insufficient EPO production or response to EPO is a major mechanism of the anemia experienced by CKD patients, which in turn causes intracellular hypoxia, as shown by our group." (PMID 28106734, 2017). "Two of these three were receiving treatment for hypertension, and one was also treated with erythropoietin injections for associated anaemia." (PMID 28948172, 2017). "In contrast to iron deficiency anemia, erythropoietin response in anemia of chronic disease is inadequate for the degree of anemia in most but not all conditions." (PMID 29348938, 2017). "In ACD rats, the administration of ASP increased ferroportin expression, mobilized iron from the liver and spleen, increased serum iron levels, caused an elevation of serum EPO, and effectively relieved the anemia." (PMID 29147463, 2017). "The complications related to reduced eGFR would be abnormal sodium balance causing hypertension, a blunted erythropoietin axis causing anemia, and disturbed calcium and phosphate balance causing secondary hyperparathyroidism and metabolic acidosis." (PMID 28367435, 2017). "Previous studies have shown that the reduced renal production of erythropoietin because of renal failure was associated with anemia." (PMID 28948119, 2017). "These drugs were supposed to cause anemia either by interfering with the absorption of micronutrients or inhibiting the effect of erythropoietin that is important for hemoglobin production." (PMID 28288159, 2017). "Recently, inflammatory processes have been proposed as the main causes of erythropoietin resistant anemia in ESRD." (PMID 28487874, 2017). "In atherogenesis, the upregulated inflammatory cytokines in the blood can suppress the synthesis of erythropoietin (EPO) and hemoglobin, which will cause chronic inflammation anemia." (PMID 29038615, 2017). "The combination of lenalidomide and EPO significantly improves the erythroid response over lenalidomide alone in patients with lower-risk non-del5q MDS with ESA-resistant anemia." (PMID 29047386, 2017). "These patients displayed the following inclusion criteria: low risk MDS, anemia refractory to erythropoiesis stimulating agents or high endogenous level of EPO (>500IU/L) and plasma ferritin (< 1000μg/l)." (PMID 29285268, 2017). "In prior work, for-profit facilities were associated with anemia overtreatment, higher than recommended hematocrit, and larger doses of erythropoietin-stimulating agents (ESAs), even after the FDA black box warning about ESAs’ harms at high doses." (PMID 29216894, 2017). "Hypoxia caused by severe anemia is a primary stimulus for myelostimulatory extramedullary hematopoiesis, whereby increased erythropoietin (EPO) production in the kidney stimulates the proliferation and maturation of erythroid precursors." (PMID 27817114, 2017). "This study supports a prudent approach of treating anemia in MM patients, aiming to maintain EPO-associated anti-MM effects, while considering bone damage." (PMID 27481313, 2016). "It is well known that AKI can contribute to the development of anaemia as a result of reduced EPO production, an increased risk of bleeding and reduced red cell life span." (PMID 26951090, 2016). "An inverse association between 25(OH)D3 levels and the EPO resistance index was observed in HD patients, and the administration of vitamin D or its analogs has been associated with improved anemia and/or reduced EPO requirements." (PMID 26933949, 2016).